FANCI (FA complementation group I)
Diseases named in the same sentence as FANCI in open-access papers (continued):
Sharing a sentence is not in itself a finding about the gene and the disease.
liver cancer (4 papers, 2022 to 2025). An epithelial or non-epithelial malignant neoplasm that arises from the liver. "Our cell experiments also demonstrate that knocking down FANCI significantly suppresses the migration and invasion capabilities of liver cancer cells." (PMID 40417238, 2025). "Overall, these results indicate that FANCI promoter methylation is significantly reduced in liver cancer compared to normal tissues, with specific methylation sites showing a strong correlation with FANCI expression." (PMID 40417238, 2025). "Results revealed that FANCI is highly expressed in liver cancer tissues, and specific downregulation of FANCI using siRNA significantly inhibited cellular migration and invasion, as demonstrated in wound-healing and Transwell assays." (PMID 40417238, 2025). "This highlights the potential role of FANCI methylation in the pathogenesis of liver cancer and its potential as a therapeutic target for LIHC gene therapy." (PMID 40417238, 2025). "Further analysis of FANCI mRNA expression in various cancer types using the Oncomine database showed that FANCI was significantly upregulated in liver cancer compared to normal tissues." (PMID 36428813, 2022). "In LIHC, hypomethylation of the FANCI promoter is significantly negatively correlated with its overexpression, suggesting that epigenetic dysregulation is one of the key mechanisms driving aberrant FANCI expression in liver cancer." (PMID 40417238, 2025). "The identification of key miRNAs and lncRNAs interacting with FANCI highlights potential regulatory mechanisms and provides insights into the molecular interactions that may influence FANCI expression and function in liver cancer." (PMID 40417238, 2025). "However, there is currently a lack of studies on the relationship between the expression of FANCI and liver cancer." (PMID 37324186, 2023). "Therefore, developing specific small-molecule inhibitors or RNA interference drugs targeting FANCI could represent a novel therapeutic strategy against malignancies such as liver cancer." (PMID 40417238, 2025). "Moreover, FANCI expression was closely linked to tumor staging and grading, particularly in LIHC, where its expression significantly increased with tumor progression, suggesting a critical role in liver cancer development." (PMID 40417238, 2025). "A significant difference in the transcription of FANCI was observed between the samples from LIHC tissue and normal tissue, with FANCI being upregulated in liver cancer." (PMID 37324186, 2023).
mesothelioma (4 papers, 2021 to 2024). A usually malignant and aggressive neoplasm of the mesothelium which is often associated with exposure to asbestos. "A Kaplan-Meier survival analysis revealed that high expressions of AUNIP, FANCI, LASP1, PSMD8, and XPO5 were clearly associated with poor OS and RFS, suggesting that the five candidate genes play important roles in the tumorigenesis and progression of mesothelioma." (PMID 35846349, 2022). "AUNIP, FANCI, LASP1, PSMD8, and XPO5 are putative antigens for the development of anti-mesothelioma mRNA vaccine and patients with the IS1 subtype may be considered for vaccination." (PMID 35846349, 2022).
cutaneous melanoma (3 papers, 2021 to 2024). A primary melanoma arising from atypical melanocytes in the skin. "Our results revealed several novel biomarkers and biological pathways that participate in the pathogenesis of cutaneous melanoma, and demonstrated the diagnostic and prognostic value of CDC45, CENPF, DTL, FANCI, GINS2, HJURP, TPX2 and TRIP13." (PMID 33531976, 2021).
glioblastoma (3 papers, 2021 to 2026). The most malignant astrocytic tumor (WHO grade IV). "In this line, FANCI knockout did not induce TMZ hypersensitivity, consistent with what was observed in an MGMT-positive subset of glioblastomas." (PMID 39656916, 2025).
lung carcinoma (3 papers, 2020 to 2025). "Our findings indicate a mechanistic model for the regulation of PRP3 by TXNL4B and the regulation of FANCI splicing isoforms by PRP3 in lung cancer that may have consequences for the susceptibility of this cancer type to radiotherapy." (PMID 37168687, 2023). "We suggest that the PRP3, serving as a splicing factor, can be modified by TXNL4B, resulting in promoting G2/M transition, EMT, and DNA repair and contributing to the observed radioresistance of lung cancer through the regulation of FANCI splicing isoforms." (PMID 37168687, 2023). "Here we reported that RPS27L also regulates ICL repair via stabilization of FANCD2 and FANCI in lung cancer cells." (PMID 33051438, 2020). "TXNL4B, interacting with PRP3, regulates FANCI splicing to produce radioresistant FANCI‐12/13 isoforms; PRP3 inhibition sensitizes lung cancer cells to radiation." (PMID 41399527, 2025).
prostate carcinoma (3 papers, 2021 to 2024). A carcinoma that arises from epithelial cells of the prostate gland. "Our results revealed that FANCI silencing alters the expression of FA pathway genes in prostate cancer cells." (PMID 38023254, 2023). "Here, we also showed that FANCI affects the expression of FA pathway genes in prostate cancer cells." (PMID 38023254, 2023). "Here, we studied the role of the whole FA pathway in prostate cancer and in particular the role of FANCI in cancer cell resistance to chemotherapy through regulation of cell cycle and DNA repair by the FA pathway." (PMID 38023254, 2023). "Our data suggest that FANCI function is a critical contributor to resistance to DNA-damaging chemotherapy in a potentially clinically identifiable subset of prostate cancers." (PMID 38023254, 2023). "As carboplatin is a known inducer of ICL-type DNA lesions, we analyzed its effect on FANCI monoubiquitination in prostate cancer cells using immunoblotting." (PMID 38023254, 2023). "Here, we report a cell line-specific dependence on FANCI and related signaling pathways to counteract the effects of DNA-damaging chemotherapy in prostate cancer." (PMID 38023254, 2023). "Our preliminary results also suggested that there are cell line-specific effects of FANCI depletion in prostate cancer cells since LNCaP cells slowed their proliferation rate in response to FANCI silencing while PC-3 cells grew normally." (PMID 38023254, 2023). "Furthermore, the expression of UBE2T (FANCT), which is needed for the ubiquitination of FANCI and which we have also shown to be upregulated in prostate cancer cells resistant to the anti-androgen therapy drug enzalutamide, was significantly reduced." (PMID 38023254, 2023). "Our current study aimed to shed light on the functional role of FANCI in prostate cancer." (PMID 38023254, 2023). "To explore which prostate cancer cell line models could be utilized to model the resistant and eradicated states, we determined the FANCI mRNA and protein expression levels in LNCaP, PC-3, 22Rv1, VCaP, and DU-145 prostate cancer cells." (PMID 38023254, 2023). "Our results also suggest that FANCI could play a major role in regulating overall FA pathway response and could be a potential drug target in prostate cancer cells." (PMID 38023254, 2023). "Furthermore, silencing of FANCI resulted in significant downregulation of several FA complex members both at mRNA and protein levels, indicating the potential regulatory function of FANCI on the FA pathway in prostate cancer cells." (PMID 38023254, 2023). "In addition, we were able to detect the carboplatin-induced FANCI monoubiquitination, indicating that FANCI becomes activated in response to chemotherapy in prostate cancer cells." (PMID 38023254, 2023).
prostate carcinoma (continued). "Prostate cancer tumor cells harboring a heterozygous deletion of FANCI were selectively eradicated by chemotherapy, while those with intact FANCI resisted chemotherapy, suggesting that FANCI could be a possible therapeutic target to convert resistant cancer cells to an eradicable state." (PMID 38023254, 2023). "Thus, we initially hypothesized that FANCI may be differently expressed in LNCaP and PC-3 prostate cancer cell lines." (PMID 38023254, 2023). "FANCI is known to be important for the repair of ICL-type DNA damage induced by chemotherapy reagents and has been also linked to treatment resistance in some other cancers, but whether it plays a role in prostate cancer was previously unknown." (PMID 38023254, 2023). "To this end, we hypothesized that prostate cancer cells exploit FA pathway-mediated DNA repair to survive the DNA-damaging effects of chemotherapy and that FANCI plays a central role in this through its ability to regulate the accumulation of other FA core complex members to the damage site." (PMID 38023254, 2023).
serous ovarian cancer (3 papers, 2022 to 2024). "When they examined the FANCI gene in carriers of FANCI c.1813C > T, they discovered that in some cases of high-grade serous ovarian cancer (HGSC), the tumor DNA showed signs of wild-type allele loss." (PMID 39767562, 2024). "We then investigated FANCI in high-grade serous ovarian carcinoma (HGSC) from FANCI c.1813C>T carriers and found evidence of loss of the wild-type allele in tumour DNA from some of these cases." (PMID 36833203, 2023). "Although the expression of FANCI protein was variable in OC tumours, it was shown to be highly expressed in normal fallopian tube epithelium, a purported tissue of origin for high-grade serous ovarian carcinoma (HGSC), the most common histopathological subtype of OC." (PMID 36833203, 2023).
bone marrow failure syndrome (2 papers, 2020 to 2022). "Mutations in FANCD2, FANCI or FA core complex components cause the FA bone marrow failure syndrome." (PMID 32725171, 2020).
Breast invasive carcinoma (2 papers, 2019 to 2023). "In Breast invasive carcinoma (BRCA) cell lines, the expression of FANCI in MCF-7 and SK-BR-3 cells exceeded that of normal breast cell line MCF-10A." (PMID 37324186, 2023). "Overexpression of DCAF13, DNMT3B, KPNA2, EXO1, FANCI, RACGAP1, and ZNF106 in invasive breast carcinoma patients showed poor survival, while overexpression of CDKN2A, SORBS1, and TP63 showed better survival." (PMID 32010179, 2019).
endometrial cancer (2 papers, 2021 to 2023). Primary or metastatic malignant neoplasm involving the endometrium (mucous membrane that lines the endometrial cavity). "In addition to well-known cancer-gene associations, we also identified that P/LP variants in BRCA1 (OR, 5.47; 95% CI, 1.42-17.17; P = .008) and FANCI (OR, 5.53; 95% CI, 1.03-19.47; P = .02) were associated with endometrial cancer." (PMID 37523182, 2023). "Pristimerin, a traditional Chinese medicine, significantly decreased the AEG-1, FANCD2 and FANCI levels in endometrial cancer cells and restored their sensitivity to cisplatin in an in vivo xenograft model." (PMID 33918653, 2021). "A positive correlation among the levels of AEG-1, FANCD2 and FANCI were observed in breast and endometrial cancers." (PMID 33918653, 2021). "AEG-1 positively regulates the expression of FANCD2 and FANCI, which regulates DNA damage by platinum compounds, and knocking out AEG-1 in endometrial cancer cells significantly increased their sensitivity to cisplatin." (PMID 33918653, 2021). "Knocking out AEG-1 increased the cisplatin sensitivity in endometrial cancer cells, but a direct role of FANCD2 and FANCI in mediating this effect was not tested by overexpression/knockdown studies." (PMID 33918653, 2021).
infertile (2 papers, 2019 to 2021). "Clearly, the study of FANCI functions is relevant for the diagnosis of cattle to diminish infertility or stillbirth cases." (PMID 31219578, 2019).
lung squamous cell carcinoma (2 papers, 2023). "For example, USP1 deubiquitinates FANCD2/FANCI or PCNA to prevent the recruitment of interstrand crosslink repair proteins and translesion DNA polymerase to inhibit DNA repair; USP7 regulates lung squamous cell carcinoma cell proliferation through MEK/ERK signaling by deubiquitinates the Raf-1." (PMID 37107644, 2023).
nasopharyngeal carcinoma (2 papers, 2017 to 2022). A carcinoma arising from the nasopharyngeal epithelium. "(2020) reported top three hub genes of PPI network of FANCI, POSTN, IFIH1, ZMYND10, PACRG and POU2AF1 for nasopharyngeal carcinoma biomarkers using STRING database PPI network construction with MCODE for module analysis." (PMID 36299526, 2022).
triple-negative breast carcinoma (2 papers, 2016 to 2019). An invasive breast carcinoma which is negative for expression of estrogen receptor (ER), progesterone receptor (PR), and human epidermal growth factor receptor 2 (HER2). "The induction of FANCI S556 phosphorylation by CTDP1 overexpression was confirmed using the triple-negative breast cancer cell line MDA-MB-231 but was lower in signal intensity than the experiments performed in 293FT cells." (PMID 31240132, 2019).
bone marrow failure (1 paper, 2019). "Since others have previously also documented successful HDR gene editing strategies to repair or compensate defects in FANCA, FANCC, FANCD1/BRCA2 and FANCI, the combined data support that gene editing can be a promising therapeutic strategy to prevent onset of bone marrow failure in FA patients." (PMID 30683899, 2019).
colorectal adenocarcinoma (1 paper, 2025). The most common type of colorectal carcinoma. "Our findings reveal that FANCI is significantly upregulated in the majority of tumor types when compared to normal tissues, with increased protein levels observed in several cancers, including colorectal adenocarcinoma (COAD) and pancreatic adenocarcinoma (PAAD)." (PMID 40417238, 2025).
Fibrolamellar carcinoma (1 paper, 2023). "Fibrolamellar carcinoma, a rare type of LIHC, expressed more FANCI than HCC." (PMID 37324186, 2023).
germ cell tumor (1 paper, 2026). A benign or malignant, gonadal or extragonadal neoplasm that originates from germ cells. "Among 25 patients with intracranial germ cell tumors, only a single case carried a P/LP germline variant, identified in FANCI." (PMID 42232602, 2026).
gynecological cancers (1 paper, 2023). "Given the identification of FANCI variants in other cancers, particularly gynecological cancers, future research should investigate the risks of these variants in view of prevention and management strategies, including childbearing considerations." (PMID 36833203, 2023).
hereditary cancer (1 paper, 2020). Malignant neoplasms occurring in families at a rate greater than that expected by chance and caused by germline mutations in a specific gene. "A prospective cohort of 1021 unrelated cancer cases with clinical suspicion of hereditary cancer was screened for mutations in the following 14 FA genes: FANCA, FANCB, FANCC, FANCD2, FANCE, FANCF, FANCG/XRCC9, FANCI, FANCL/PHF9, FANCM, FANCP/SLX4, FANCQ/ERCC4, FANCR/RAD51 and FANCU/XRCC2." (PMID 32235514, 2020).
hypogonadism (1 paper, 2019). A disorder characterized by decreased function of the gonads. "As ovaries are too small to be easily detected by this technique, we performed classical H&E histological staining on gonad sections, confirming a hypogonadism in all FANCI knockout animals." (PMID 31219578, 2019).
Immunodeficiency (1 paper, 2022). Failure of the immune system to protect the body adequately from infection, due to the absence or insufficiency of some component process or substance. "Germline mutations in the FANCI and RAD51 genes might impair the patient’s DNA repair ability, leading to a degree of immunodeficiency and tumour susceptibility." (PMID 35280783, 2022). "However, germline mutations in the FANCI and RAD51 genes might impair the DNA repair ability, lead to a certain degree of immunodeficiency and tumour susceptibility of the patients, and thereby make the patients sensitive to pathogen infection, ionizing radiation, and other damages." (PMID 35280783, 2022).
male infertility (1 paper, 2025). The inability of the male to effect fertilization of an ovum after a specified period of unprotected intercourse. "For example, the V555F variant, which causes male infertility through Sertoli only syndrome, completely lacks ATPase activity while retaining normal FANCD2:FANCI monoubiquitination stimulation." (PMID 40447800, 2025).
polycystic ovary syndrome (1 paper, 2019). A disorder that manifests as multiple cysts on the ovaries. "Moreover, the genome-wide association studies (GWAS) in European ancestry populations suggest that FANCC is a high risk locus of polycystic ovary syndrome, and FANCI is implicated in age at menopause." (PMID 31535215, 2019).
serous carcinoma (1 paper, 2024). "Tissue expression of FANCI was evaluated in normal fallopian tubes and in those with high-grade serous carcinoma." (PMID 39767562, 2024).
squamous cell carcinoma (1 paper, 2023). A carcinoma arising from squamous epithelial cells. "Further assessment of cancers in individuals harbouring germline FANCI c.1813C>T or somatic FANCI variants may elucidate a genetic signature associated with FANCI, as has been reported for FA-associated squamous cell carcinomas." (PMID 36833203, 2023).